PRDX6 (peroxiredoxin 6)
Diseases named in the same sentence as PRDX6 in open-access papers (continued):
Sharing a sentence is not in itself a finding about the gene and the disease.
breast carcinoma (continued). "In this study, we investigated the effects of peroxiredoxin 6 on the proliferation and metastatic potential of human breast cancer cells and their potential mechanism." (PMID 17980029, 2007). "In an in vivo study, we also demonstrated that peroxiredoxin 6-transfected breast cancer cells grew much faster and had more pulmonary metastases than control cells." (PMID 17980029, 2007). "Conversely, experimental inhibition of PRDX6 expression decreased the invasive and potential potential of breast cancer cells, partially through regulation of uPAR, Ets-1, MMP-9, RhoC and TIMP-2 expression." (PMID 17980029, 2007). "In this study, our results suggested that the effect of PRDX6 on the invasive and metastatic potential of breast cancer cells was mediated partially through regulation of RhoC expression." (PMID 17980029, 2007). "Studies have reported that PRDX6 was overexpressed in breast cancer." (PMID 38544826, 2024). "Our results showed that the low expression levels of PRDX6 could inhibit the growth of cancer cells, which were in accord with the results of esophageal carcinoma, breast cancer." (PMID 34246267, 2021). "The repeated experimental results are consistent with the previously reported findings in the original study and the functional role for PRDX6 in malignant progression of human cancer including breast cancer has been widely documented and recognized in numerous other studies." (PMID 29966525, 2018). "In addition, the overexpression of PRDX6 leads to a more invasive phenotype and metastatic potential of human breast cancer." (PMID 24932247, 2014). "However to our present knowledge, only two 1q genes, COX2 and peroxiredoxin-6/PRDX6 have thus far been found to be overexpressed in breast cancer and to have key roles in metastasis and cancer cell survival." (PMID 23460839, 2013). "Furthermore, they demonstrated that overexpression of PRDX6 in breast cancer cells promoted their invasive and metastatic potential in vitro and in vivo." (PMID 22200848, 2012). "The results of adhesion and invasive assays in vitro also showed that PRDX6 could promote the invasion and migration of breast cancer cells." (PMID 17980029, 2007). "Karihtala and colleagues found that PRDXs, including PRDX6, were overexpressed in breast cancer." (PMID 17980029, 2007). "However, until now, there was little information about the role of PRDX6 in the metastasis of cancers, including breast cancer." (PMID 17980029, 2007). "Furthermore, we demonstrated that overexpression of PRDX6 in breast cancer cells promoted their invasive and metastatic potential in vitro and in vivo." (PMID 17980029, 2007). "Liu and colleagues reported that in a MDR (multidrug resistant) cell line MCF7/AdVp3000 the expression of PRDX6 was increased and the expression of PRDX2 was decreased, which suggested they might cause drug resistance to chemotherapy in breast cancer." (PMID 17980029, 2007). "Although PRDX6 is involved in various cancers, its role in breast cancer (BRCA) remains unclear." (PMID 40583735, 2025). "However, in the ncRNA-eQTL database, only the rs2067079 variant demonstrated a trans-eQTL effect on RP11-713C19.2 (ENSG00000213331.4, PRDX6, peroxiredoxin 6, processed pseudogene) in three cancer types (breast cancer, head and neck carcinoma, and hepatocellular carcinoma)." (PMID 40234289, 2025). "Furthermore, high levels of PRDX6 have been reported with an invasive phenotype in breast cancer." (PMID 34246267, 2021). "However, how PRDX6 regulates RhoC and TIMP-2 as well as whether PRDX6 is an instigator of metastasis or merely a correlative product during progression of breast cancer are still beyond present understanding." (PMID 22200848, 2012). "This provided direct evidence that PRDX6 could enhance the invasive potential of breast cancer." (PMID 17980029, 2007).
breast carcinoma (continued). "The Mann-Whitney U test showed that five AAbs (HSPA4, PRPF19, ENO1, PRDX6, and MMP14) were significantly higher in the breast cancer group than in the control group." (PMID 40766308, 2025). "Anti-HSPA4, anti-PRPF19, anti-ENO1, anti-PRDX6, and anti-MMP14 autoantibodies showed significant increases in breast cancer patients." (PMID 40766308, 2025). "We validated these five autoantibodies (HSPA4, ENO1, PRDX6, PRPF19, and MMP14) in an independent cohort of 33 breast cancer patients and 45 healthy controls." (PMID 40766308, 2025). "Five potential AAb biomarkers (HSPA4, ENO1, PRDX6, PRPF19, MMP14) predictive of breast cancer were identified through verification and validation cohorts." (PMID 40766308, 2025). "In the verification cohort, IgG autoantibodies against HSPA4, ENO1, PRDX6, PRPF19 and MMP14 were significantly increased in breast cancer patients with areas under the curve (AUCs) of 0.90, 0.89, 0.82, 0.78 and 0.77, respectively." (PMID 40766308, 2025). "Using this methodology, we identified nine proteins—FN1, VWF, PRG4, MMP9, CLU, PRDX6, PPBP (CXCL7), APOC1, and CHL1—that were robustly quantified in serum and showed statistically significant differences between breast cancer patients and healthy controls." (PMID 40940928, 2025). "ELISA was performed to confirm the altered expression levels of PRDX2, PRDX6, CTSB and CTSD in the serum among the breast cancer patients and healthy volunteers as a representative sample in order to validate the serum levels." (PMID 24932247, 2014). "Chang and colleagues found that PRDX6 is up-regulated in highly invasive and potentially metastatic MDA-MB-231 HM breast cancer cells compared with their parental cells." (PMID 22200848, 2012). "We identified upregulation of PRDX6 in highly invasive and potentially metastatic MDA-MB-231HM breast cancer cells compared with their parental cells." (PMID 17980029, 2007). "However, the role of PRDX6 in breast cancers remains unknown." (PMID 17980029, 2007). "Interestingly, the expression patterns of PRDX6 in BRCA were contrary in different dataset, such as mRNA expression levels of PRDX6 decreased in TCGA dataset, while protein levels increased in breast cancer cells, which may be caused by individual difference, race, cancer subtypes." (PMID 34246267, 2021). "Notably, established protein biomarkers for metastatic breast cancer, such as EGFR, HSPD1, PRDX6, and TPM4, which are related to lymph node and regional metastasis, were also detected." (PMID 32489334, 2020). "Karihtala and colleagues observed that staining for PRDX2 and PRDX6 was negative in half of breast cancer cases, whereas PRDX1, PRDX3, PRDX4 and PRDX5 showed stronger expression levels." (PMID 17980029, 2007). "However, we do not know whether PRDX6 is an instigator of metastasis or merely a correlative product during progression of breast cancer." (PMID 17980029, 2007).
Alzheimer disease (14 papers, 2012 to 2025). A progressive, neurodegenerative disease characterized by loss of function and death of nerve cells in several areas of the brain leading to loss of cognitive function such as memory and language. "Oxidative stress has been implicated in the pathogenesis of Alzheimer’s disease, and brains with the disease examined in this study also exhibited higher carbonylated proteins, as well as an increased thiol oxidation state of peroxiredoxin 6 (Prx6)." (PMID 33567524, 2021). "Oxidative stress has been implicated in the pathogenesis of Alzheimer's disease, and Alzheimer's disease brains examined in this study also exhibited higher carbonylated proteins as well as increased thiol oxidation state of peroxiredoxin 6 (Prx6)." (PMID 33052346, 2020). "Furthermore, PRDX6 protein expression in astrocytes has already been associated with Alzheimer disease where it might function as an antioxidant enzyme suggesting that PRDX6 might be involved in neurological diseases." (PMID 23210548, 2012). "Over the past several years, Prdx6 has been extensively investigated in brain diseases, such as Alzheimer’s disease (AD) and Parkinson’s disease (PD)." (PMID 38671897, 2024). "Prdx6 upregulation has been reported as a defensive compensatory reaction to the oxidative damage in patients and animal models of Parkinson’s disease, Alzheimer’s disease, Pick’s disease, amyotrophic lateral sclerosis, glioma, and traumatic brain injury." (PMID 36290607, 2022). "Commonly increased in the CA1 and thalamus was the glutathione peroxidase enzyme Prdx6, shown to mediate protection by astrocytes in Alzheimer's disease." (PMID 35651626, 2022). "Indeed, Prdx6 overexpression accelerates the development of Parkinson’s disease, Alzheimer’s disease, and experimental autoimmune encephalomyelitis in animal models." (PMID 36290607, 2022). "PRDX6 is an antioxidant protein which mainly exists in glia and keeps increasing as growing, it may have important roles in alzheimer’s disease and parkinson’s disease." (PMID 28222113, 2017). "Additionally, Prdx6 is upregulated in patients with Alzheimer’s disease and ALS, suggesting a potential role in neurodegenerative disease." (PMID 23922950, 2013). "PRDX6 is already suspected to play a role in neurodegeneration since it was found to be highly expressed in reactive astrocytes of PD‐ and dementia with lewy body patients as well as astrocytes in close proximity to diffuse abeta plaques in Alzheimer's disease patients." (PMID 40071644, 2025). "In particular, Prdx6 was commonly increased in the CA1 and thalamus and is known to be protective in Alzheimer's disease." (PMID 35651626, 2022).
ovarian carcinoma (14 papers, 2014 to 2025). A malignant neoplasm originating from the surface ovarian epithelium. "We then mutated both lysine 23 and 210 residues of NNMT‐GFP to arginine simultaneously (K23R/K210R), and found the K23R/K210R double mutation of NNMT markedly impeded the reduction of NNMT protein level caused by PRDX6 KO in ovarian cancer cells." (PMID 39887931, 2025). "To investigate the nonenzymatic mechanism underlying PRDX6's tumor‐promoting function in ovarian cancer, we performed an integrated screening strategy to identify the direct downstream targets of PRDX6." (PMID 39887931, 2025). "The decreased growth of ovarian cancer cells caused by PRDX6 KO was mainly attributed to impaired proliferation abilities as evidenced by 5‐ethynyl‐2′‐deoxyuridine (EdU) assay, but not induction of apoptosis." (PMID 39887931, 2025). "Among the six PRDX members, only the expression of PRDX6 was positively associated with worse overall survival and progression‐free survival of ovarian cancer patients." (PMID 39887931, 2025). "Meanwhile, the curves showed that high PRDX6 mRNA expression was associated with poorer PFS for all ovarian cancer patients and endometrioid cancer patients." (PMID 30104402, 2018). "PRDX6 overexpression was linked with a poorer OS in all ovarian cancer patients treated with Taxol and Taxol+Platin chemotherapy." (PMID 30104402, 2018). "Notably, PRDX6 overexpression is associated with higher NNMT protein levels in human ovarian cancer tissues and is predictive of poor prognosis of ovarian cancer patients." (PMID 39887931, 2025). "Moreover, we evaluated the association of PRDX6 with the survival of ovarian cancer patients, and found that higher PRDX6 protein level was correlated with shorter overall and progression‐free survival, respectively." (PMID 39887931, 2025). "PRDX6 overexpression is also associated with poor prognosis and overall survival in ovarian cancer." (PMID 34320944, 2021). "Similarly, NNMT KD could also rescue the enhanced ovarian cancer growth and metastasis caused by PRDX6‐MUT overexpression in both subcutaneous and peritoneal metastatic xenograft mice models, respectively." (PMID 39887931, 2025). "Similar rescuing phenotypes were also observed for the migration and invasion of PRDX6 KO ovarian cancer cells." (PMID 39887931, 2025). "We next interrogated the clinical relevance of PRDX6‐mediated NNMT upregulation in ovarian cancer using a tissue microarray containing 147 cases of human ovarian cancer." (PMID 39887931, 2025). "Both the enzymatic and nonenzymatic functions contribute to this tumor‐promoting role of PRDX6 in ovarian cancer." (PMID 39887931, 2025). "Regarding ovarian cancer, overexpression of peroxiredoxin 6 leads to the inhibition of cisplatin-induced apoptosis." (PMID 41187427, 2025). "This study unravels a crucial oncogenic mechanism of the antioxidant enzyme PRDX6 in ovarian cancer beyond its enzymatic mechanisms." (PMID 39887931, 2025). "Collectively, these results indicate that PRDX6 promotes the growth, migration, and invasion of ovarian cancer cells in vitro." (PMID 39887931, 2025). "Taken together, these data demonstrate that PRDX6 is upregulated in ovarian cancer, at least in part, due to copy number gain and amplification." (PMID 39887931, 2025). "Overall, the findings illustrate a critical oncogenic mechanism of the antioxidant enzyme PRDX6 in promoting ovarian cancer progression beyond its enzymatic mechanisms." (PMID 39887931, 2025). "Our findings provide novel insights into the oncogenic mechanism of the PRDXs family and suggest the PRDX6‐NNMT axis as a potential treatment target for ovarian cancer." (PMID 39887931, 2025). "In contrast, ectopic expression of PRDX6 profoundly promoted the growth and proliferation of ovarian cancer cells." (PMID 39887931, 2025).
ovarian carcinoma (continued). "We then analyzed the TCGA, GTEx, and GSE26712 datasets, and found that the mRNA level of PRDX6 was significantly upregulated in human ovarian cancer tissues compared with normal ovarian tissues." (PMID 39887931, 2025). "Taken together, these data indicate that PRDX6‐mediated NNMT upregulation can be potential biomarkers to predict the prognosis of ovarian cancer patients." (PMID 39887931, 2025). "Consistently, PRDX6 KO‐mediated suppression of migration and invasion of ovarian cancer cells were markedly rescued by overexpressing NNMT‐K23R/K210R mutant." (PMID 39887931, 2025). "Genomic analysis of the TCGA database revealed a remarkable amplification of PRDX6 copy number in ovarian cancer tissues." (PMID 39887931, 2025). "In support of this observation, immunoblotting analysis revealed an obvious decrease in NNMT protein level upon PRDX6 KO or knockdown (KD) by siRNA in ovarian cancer cells." (PMID 39887931, 2025). "Together, these results suggest that PRDX6 promotes the growth and metastasis of ovarian cancer cells by upregulating NNMT in vitro." (PMID 39887931, 2025). "We further examined the impact of PRDX6 on the metastatic potential of ovarian cancer cells by performing wound healing assay and transwell assay." (PMID 39887931, 2025). "Overall, these findings suggest that PRDX6 promotes the growth and metastasis of ovarian cancer cells in vivo by upregulating NNMT." (PMID 39887931, 2025). "Given the pathological role of PRDX6 in ovarian cancer, we sought to investigate the biological function of PRDX6 in ovarian cancer progression in cultured ovarian cancer cells." (PMID 39887931, 2025). "It has been reported that overexpression PRDX6 participates in cisplatin resistance in ovarian cancer and predicts poor OS and PFS." (PMID 31402980, 2019). "Elevated expression of PRDX3, PRDX5, and PRDX6 mRNAs showed poorer overall survival (OS); PRDX5 and PRDX6 also predicted poor progression-free survival (PFS) for ovarian cancer patients." (PMID 31315664, 2019). "Meanwhile, elevated expression of PRDX3, PRDX5, and PRDX6 mRNAs showed poorer overall survival (OS); PRDX5 and PRDX6 also predicted poor progression-free survival (PFS) for ovarian cancer patients." (PMID 30104402, 2018). "In the present study, our results using HPA database showed that increased PRDX6 protein expression in ovarian cancer tissues compared with normal ovarian tissues." (PMID 30104402, 2018). "Elevated expression of PRDX6 mRNA was associated with poorer PFS in stages I and II ovarian cancer patients, whereas PRDX6 in stages III and IV ovarian cancer patients displayed better PFS." (PMID 30104402, 2018). "By analyzing the KM plotter database, we reported for the first time that PRDX6 overexpression was linked with a poorer OS for all ovarian cancer patients and grade III ovarian cancer patients." (PMID 30104402, 2018). "According to our results, high levels of PRDX3, PRDX5, and PRDX6 indicated poor clinical outcomes in ovarian cancer." (PMID 30104402, 2018). "In comparison, there were 12 cases of ovarian cancer tissues tested, with 1 case of high, 5 cases of medium and 4 cases of low PRDX6 staining." (PMID 30104402, 2018). "It was found that high levels of PRDX6 mRNA were correlated to a poorer OS for all ovarian cancer patients." (PMID 30104402, 2018). "Many studies have demonstrated that PRDX6 promotes invasion and metastasis of a variety of cancer cells including lung, breast, and ovarian cancer cells." (PMID 24618722, 2014). "In addition, a peritoneal metastatic xenograft model was also established to evaluate the effect of PRDX6‐NNMT axis on ovarian cancer metastasis in vivo." (PMID 39887931, 2025). "In addition, PRDX6 mRNA level was significantly higher in patients with stage III‐IV ovarian cancer compared to those with stage I‐II disease." (PMID 39887931, 2025). "We next asked how the PRDX6 mRNA level is increased in ovarian cancer." (PMID 39887931, 2025).